WNT3A (Wnt family member 3A)
Diseases named in the same sentence as WNT3A in open-access papers (continued):
Sharing a sentence is not in itself a finding about the gene and the disease.
colitis (3 papers, 2019 to 2024). Inflammation of the colon. "Forty-eight genes with SNP/InDel mutation were overlapped in the three colitis tissues, two (Wnt3a and Lama2) of which are in the cancer development-related signaling pathway." (PMID 34764977, 2021). "Furthermore, our results showed that Wnt3a were significantly upregulated in the DSS-induced colitis group." (PMID 38280896, 2024). "Our study found that TRPM8, TAC1 and WNT3A expression were significantly correlated with the severity of ulcerative colitis in patients and DSS-induced colitis in mice." (PMID 38280896, 2024).
colon adenocarcinoma (3 papers, 2017 to 2024). "Similarly, CRISPR activation–mediated (CRISPRa-mediated) SELENOP overexpression in RKO cells or MC38 (mouse colon adenocarcinoma) cells augmented WNT3A-induced TOPFlash activity." (PMID 37166989, 2023). "miR-1307–3p has low expression levels in colon adenocarcinoma tissues and cell lines, can regulate proliferation and apoptosis of colon adenocarcinoma cells via targeting ISM1 and regulating activation of Wnt3a/β-catenin signaling pathway." (PMID 39305404, 2024). "To investigate drug responses in the 3D cultures, we established 3D tumoroids from a resected colon adenocarcinoma and cultured these in the absence of WNT3A as previously shown." (PMID 28977993, 2017).
embryonic carcinoma (3 papers, 2011 to 2015). "Wnt3a contributes to the post-translational regulation and activation of MyoD and MyoG during myogenesis in P19 embryonal carcinoma stem cells." (PMID 26247931, 2015). "Wnt3a has been shown to enhance the generation of multipotential mesendodermal (including myogenic) progenitors from embryonic stem cells and the myogenic differentiation of P19 embryonic carcinoma cells." (PMID 25651906, 2015). "In addition, Wnt3a and β-catenin are required for muscle-specific gene transcription in embryonic carcinoma cells and satellite-cell proliferation during adult skeletal muscle regeneration." (PMID 21970630, 2011).
endometrial cancer (3 papers, 2019 to 2022). Primary or metastatic malignant neoplasm involving the endometrium (mucous membrane that lines the endometrial cavity). "MicroRNA-15a inhibits endometrial cancer cell growth through Wnt/β-catenin signaling by repressing WNT3A." (PMID 31737898, 2019). "miR-15a-5p overexpression decelerates endometrial cancer cell growth by directly targeting Wnt3a." (PMID 35428780, 2022).
endometriosis (3 papers, 2013 to 2024). The growth of functional endometrial tissue in anatomic sites outside the uterine body. "Further studies are required whether overexpression of Wnt3a is one of the underlying mechanisms for the development of fibrosis in endometriosis." (PMID 26056600, 2014). "Collagen gel contraction in Wnt3a-treated endometrial cells was comparable with that of the endometrium of patients with endometriosis." (PMID 24124596, 2013). "Molecular docking analyses further underscored a substantive interaction between AGPAT4 and Wnt3a.Our study highlights AGPAT4’s key role in endometriosis, influencing endometrial stromal cell behavior, and identifies AGPAT4 pathways as promising therapeutic targets for this condition." (PMID 38850428, 2024). "Treatment with Wnt3a induced clearly visible αSMA-positive stress fibers, the hallmark of activated myofibroblasts, in endometrial stromal cells of patients without endometriosis." (PMID 26056600, 2014). "Cell-mediated contraction of collagen gel in stromal cells of patients without endometriosis was increased by treatment with Wnt3a to a level comparable with that of patients with endometriosis." (PMID 26056600, 2014). "In vitro effects of activation of the Wnt/β-catenin signaling pathway by treatment with recombinant Wnt3a on profibrotic responses were evaluated in endometrial stromal cells of patients without endometriosis." (PMID 24124596, 2013). "Wnt3a treatment in stromal cells of patients without endometriosis increased collagen gel contraction to a level comparable with that of the endometrium from patients with endometriosis." (PMID 24124596, 2013). "In the present study, we also found that Wnt3a treatment in the endometrium of patients without endometriosis significantly increased stromal cell proliferation and migration, stromal cell-mediated contraction of collagen gels, and expression of fibrotic marker genes." (PMID 24124596, 2013). "Thus, in the present study, we attempted to activate the Wnt/β-catenin signaling pathway by recombinant Wnt3a in the endometrium of patients without endometriosis." (PMID 24124596, 2013).
head and neck cancer (3 papers, 2021 to 2023). A primary or metastatic malignant neoplasm affecting the head and neck. "Recent reports have demonstrated that Wnt3a promotes radioresistance via autophagy, whereas the epigenetic repression of autophagy-related p62 protein overcomes radioresistance in head and neck cancer." (PMID 36890567, 2023). "In head and neck cancer, the level of WNT3A was increased in patients’ serum, which enhanced radioresistance by WNT/β-catenin pathway activation in NPC cells, and it may represent an independent prognostic factor in laryngeal squamous cell carcinoma." (PMID 34287269, 2021).
Insulin resistance (3 papers, 2016 to 2023). Increased resistance towards insulin, that is, diminished effectiveness of insulin in reducing blood glucose levels. "Under the similar hyperglycaemia condition in STZ‐induced diabetic rat, Wnt3a/β‐catenin pathway was found to be inhibited in cardiomyocytes, but swimming exercise was proved to alleviate insulin resistance through inhibiting the overactivated Wnt3a/β‐catenin pathway in skeletal muscles." (PMID 34042263, 2021). "Notably, in T2D and chronic insulin resistance, we observed Wnt3a downregulation and Wnt4 upregulation in both skeletal muscle and WAT." (PMID 27527335, 2016). "Thus, the higher Wnt3a expression and simultaneous downregulation of Wnt4, as reported herein, appear to be involved in the compensatory mechanism of lipid-induced insulin resistance in skeletal muscle and WAT." (PMID 27527335, 2016). "The present study found that two Wnt proteins, WNT3a and WNT4, are specifically secreted by skeletal muscle and WAT during the development of insulin resistance and play an important role in crosstalk between insulin-resistant tissues and pancreatic β-cells." (PMID 27527335, 2016). "The present data suggest that WNT3a and WNT4 are important components of crosstalk between insulin-resistant tissues and the pancreas in maintaining β-cell adaptation to systemic insulin resistance." (PMID 27527335, 2016). "Here, we show that two Wnt proteins, WNT3a and WNT4, are specifically secreted by skeletal muscle and adipose tissue during the development of insulin resistance and play an important role in cross-talk between insulin-resistant tissues and pancreatic beta cells." (PMID 27527335, 2016).
nonalcoholic fatty liver disease (3 papers, 2016 to 2022). "Our study also found that the increased expression of HMGCS2 in the HFD-fed mice is associated with Wnt3a/β-catenin abundance in nonalcoholic fatty liver disease." (PMID 33647884, 2021). "The aims of the present study were to evaluate the polarization of liver macrophages and the possible role of Wnt3a production by macrophages in hepatic progenitor cell response in the progression of pediatric non-alcoholic fatty liver disease." (PMID 27310371, 2016). "In conclusion, macrophage polarization seems to have a key role in the progression of pediatric non-alcoholic fatty liver disease; the modulation of macrophage polarization could drive hepatic progenitor cell response by Wnt3a production." (PMID 27310371, 2016).
oral cancer (3 papers, 2019 to 2024). "Recent research indicated that hsa−miR−216a−3p manipulates cell hyperplasia in oral cancer through Wnt3a/β−catenin signaling." (PMID 39882244, 2024). "On one hand, it was found to act as an oncomiR in oral cancer through affecting the Wnt3a/β−catenin pathway." (PMID 39906666, 2024).
oral squamous cell carcinoma (3 papers, 2017 to 2020). "Previous reports have suggested that other mechanisms may be involved in regulation of CTHRC1, such as TGF-β and Wnt3a pathway activation in gastric and oral squamous cell carcinoma, respectively." (PMID 28645305, 2017).
orofacial cleft (3 papers, 2023 to 2025). A disorder of facial skeleton that is characterized by cleft lip and/or cleft palate that result in feeding, speech and hearing problems caused by failures during development. "The main aim of this specific study is to assess the presence of SHH, SOX3, WNT3A and WNT9B proteins by immunohistochemistry within the non-syndromic cleft-affected epithelium and connective tissue in non-syndromic orofacial cleft patient groups together with a comparison with the control group." (PMID 37366674, 2023).
teratocarcinoma (3 papers, 2008 to 2023). A germ cell tumor characterized by the presence of an embryonal carcinoma component and a teratoma component. "Furthermore, it has been reported that treatment of F9 teratocarcinoma cells with Wnt-3a activates a Gαq-mediated phosphatidylinositol signaling, which results in generating inositol polyphosphates such as IP5." (PMID 37481708, 2023). "We focused on a molecule that blocked Wnt-induced reporter activity and also repressed Axin2 expression in 10T1/2 cells and SAX1 and GAD1 expression in teratocarcinoma cells induced with exogenous Wnt3a (data not shown)." (PMID 18698373, 2008). "In teratocarcinoma cell lines PA-1 and NTERA-2, YW211.31 antibody inhibits reporter activity induced by autocrine Wnt signaling with similar potency to that observed with exogenous Wnt3a (data not shown)." (PMID 20856934, 2010).
-cerebrovascular diseases (2 papers, 2021 to 2024). "Functional mutations of the WNT3A gene may have an impact on the etiology of cardio-cerebrovascular diseases." (PMID 39329917, 2024). "Functional mutations in WNT3A gene may affect the pathogenesis of cardio-cerebrovascular diseases." (PMID 34322525, 2021).
allergic asthma (2 papers, 2022 to 2023). A asthma with a basis in a pathological type I hypersensitivity reaction. "Moreover, Wnt-3a expression directly affects human mast cells to produce the chemokines IL-8 and CCL8 and can further promote the development of allergic asthma." (PMID 36463267, 2022).
ameloblastoma (2 papers, 2017 to 2022). The most common odontogenic tumor, arising from the epithelial component of the embryonic tooth and usually affecting the molar-ramus region of the mandible or maxilla. "While AM-3 cells spontaneously produced high amount of MMP-9 and had potential to increase MMP-9 production in response to Wnt-3a, this study demonstrated that AM-3 ameloblastoma cells showed higher expression of MMP-2 by the treatment of MC3T3-E1 osteoblast CM." (PMID 35243014, 2022). "In that study, we have shown that Wnt‐3a promotes the expression of MMP‐9 from ameloblastoma cells." (PMID 29226086, 2017).
Anxiety (2 papers, 2023 to 2024). Intense feelings of nervousness, tension, or panic often arise in response to interpersonal stresses. "Conversely, a single injection of WNT3A into the brains of wild-type embryonic mice cause anxiety and memory alterations." (PMID 38383780, 2024). "WNT3A-treated mice showed reduced anxiety levels based on the elevated-plus maze paradigm and marble-burying test, which indicated that transient WNT–β-catenin activation during embryonic brain development mimics the ID caused by KDM5C mutations." (PMID 38383780, 2024). "To summarize, both Wnt3a and Lip-1 treated mice showed less anxiety and spatial memory deficits after TBI." (PMID 37624470, 2023).
apical periodontitis (2 papers, 2019 to 2024). "“SNPs in WNT3, WNT3A, WNT5A, WNT8A, WNT9B, and WNT11 genes” were examined to check their association with apical periodontitis." (PMID 39723289, 2024). "The polymorphic variations on the genes WNT3 and WNT3A were associated with increased susceptibility to apical periodontitis, specifically an intronic SNP in WNT3 (rs9890413) and a promoter SNP in WNT3A (rs1745420)." (PMID 31379856, 2019).
atherosclerosis (2 papers, 2019 to 2022). A disease characterized by the build-up of fatty material and calcium deposition in the arterial wall resulting in partial or complete occlusion of the arterial lumen. "WISP‐2 was upregulated in human atherosclerosis and partly co‐localized with Wnt3a." (PMID 30548452, 2019). "Similar to Wnt3a, WISP‐2 protein was also upregulated in atherosclerosis compared to non‐diseased arteries (2.64 ± 0.2‐fold, n = 11 plaque and n = 4 non‐diseased, p < 0.05)." (PMID 30548452, 2019). "This study reports, for the first time, upregulation of Wnt3a and WISP‐2 proteins in atherosclerosis near to macrophages and fibrous cap VSMCs, implying a role for these pro‐survival factors in disease." (PMID 30548452, 2019). "We report that Wnt3a and WISP‐2 are upregulated in human atherosclerosis." (PMID 30548452, 2019).
cardiac hypertrophy (2 papers, 2018 to 2025). "Second, previous studies have demonstrated that Wnt3a is not only closely associated with cardiac fibrosis but also that its upregulation is linked to myocardial hypertrophy." (PMID 40407710, 2025). "To further validate a role for Wnt signaling in mediating cardiac hypertrophy, we treated rat primary cardiomyocytes with recombinant Wnt3a." (PMID 29895976, 2018).
clear cell renal carcinoma (2 papers, 2015 to 2023). A malignant epithelial neoplasm of the kidney characterized by the presence of lipid-containing clear cells within a vascular network. "For example, it was previously indicated that SOSTDC1 is significantly down-regulated in clear cell renal carcinoma and over-expression of SOSTDC1 inhibits its proliferation through suppressing BMP-7-induced phosphorylation of Smad-1, -5, and -8, as well as Wnt-3a signaling." (PMID 26378658, 2015).
cleft lip/palate (2 papers, 2021 to 2024). Cleft lip and palate is a fissure type embryopathy extending across the upper lip, nasal base, alveolar ridge and the hard and soft palate. "Bone mineral density variation and cleft palate have been linked to the WNT3A rs752107 polymorphism." (PMID 39329917, 2024). "WNT3A rs752107 polymorphism was identified to be associated with cleft palate and bone mineral density variation." (PMID 34322525, 2021).
Cognitive impairment (2 papers, 2024 to 2025). Abnormal cognition is characterized by deficits in thinking, reasoning, or remembering. "Pharmacological interventions revealed that the PI3K‐AKT inhibitor LY294002 (0.8 μM in 0.5 μL) but not IGFR1 antagonist JB‐1 (0.8 μM in 0.5 μL) completely abolished WNT3a‐mediated improvements in neuropathic pain behaviors and cognitive impairment in SNI mice." (PMID 41414737, 2025).
colorectal adenocarcinoma (2 papers, 2016 to 2024). The most common type of colorectal carcinoma. "Human colorectal adenocarcinoma HT-29 cells were treated with TQ (60 μM) and 15 μM Wnt3a inhibitor (LGK974) for 48 h." (PMID 38532470, 2024).
COVID-19 (2 papers, 2023 to 2025). A disease caused by infection with severe acute respiratory syndrome coronavirus 2. "Consistently, virally induced downregulation of Wnt3a could contribute to BBB permeability in COVID-19/Long COVID." (PMID 41156605, 2025). "Further studies are warranted to fully understand the molecular mechanisms underlying the relationship between Wnt3a, the Wnt/β-catenin pathway, and SARS-CoV-2 infection, which could potentially lead to the development of novel therapeutics for COVID-19." (PMID 38203386, 2023).
craniosynostosis (2 papers, 2021 to 2026). Craniosynostosis is defined as the premature fusion of one or more cranial sutures leading to secondary distortion of skull shape resulting in skull deformities with a variable presentation. "CircPROSC promotes craniosynostosis by sponging miR‐6815‐5p, thereby activating WNT3A/β‐catenin signaling and enhancing RUNX2‐mediated osteogenesis." (PMID 41178597, 2026). "Here the authors isolate Wnt responsive skeletal stem and progenitor cells from sutures, that can be transplanted together with Wnt3a protein to repair craniosynostosis in a mouse model." (PMID 34330896, 2021).
degenerative disc disease (2 papers, 2016 to 2023). "Our data suggest that HBO inhibiting the Wnt3a/β-catenin signaling pathway by upregulating miR-107 expression in human degenerated disc may be feasible as a therapeutic for degenerative disc disease." (PMID 37626921, 2023).
depression (2 papers, 2020 to 2025). "As in the case of psoriasis, inhibiting the CD19 expression caused an increase in the concentration of PPARγ, Wnt3a, and β-catenin; therefore, it is probable that CD19 regulates the symptoms of psoriasis and depression through the PPARγ/β-catenin/Wnt3a signaling pathway." (PMID 40141110, 2025). "Consequently, the downregulation of WNT3A, GAGA3, and CHRNA6 may account for the DTMUV-induced depression and neurological symptoms." (PMID 32244328, 2020).
diabetic retinopathy (2 papers, 2023 to 2024). "Compared with control, the expression of Wnt3a increased in diabetic retinopathy mice measured by semi-quantitative analysis (P < 0.05)." (PMID 37037887, 2023). "Similarly, PDLIM1 directly regulates Wnt3a expression, influencing cell migration and invasion in diabetic retinopathy." (PMID 39548074, 2024).
dysplasia (2 papers, 2019 to 2021). A usually neoplastic transformation of the cell, associated with altered architectural tissue patterns. "A loss of Wnt3a expression was observed beginning from the metaplastic cell line CP-A towards dysplasia (CP-B) and EAC (OE33 and OE19), confirmed by a lower staining index of WNT3A in Barrett’s metaplasia and EAC, than in squamous epithelium specimens." (PMID 30841855, 2019). "Oral moderate and severe dysplasia samples showed higher intensity of Wnt3a when compared to healthy oral mucosa and mild dysplasia samples (p <0.01)." (PMID 34564680, 2021). "Of all the dysplasia and OSCC samples analyzed (n=60), 100% of epithelial cells expressed Wnt3a in all epithelium strata but, unexpectedly, it was not expressed in the healthy oral mucosa (n=3)." (PMID 34564680, 2021).
germ cell tumor (2 papers, 2019 to 2022). A benign or malignant, gonadal or extragonadal neoplasm that originates from germ cells. "Myogenesis was identified in this screen, including myogenesis of germ cell tumor lines (2 genes, NKX2-5 and WNT3A, page 320, p = 0.00177, cannabis dependence) and myogenesis of carcinoma cell lines (2 genes, NKX2-5 and WNT3A, page 320, p = 0.00177)." (PMID 35897396, 2022).
Hypertension (2 papers, 2021 to 2023). The presence of chronic increased pressure in the systemic arterial system. "Since Wnt/β-catenin pathway and RAS regulate positively each other during hypertension, the decreased WNT3A expression may lead to inactivation of RAS which has a major role in the pathophysiology of hypertension." (PMID 34322525, 2021).
kidney injury (2 papers, 2021 to 2022). Trauma to the kidney. "In summary, we have demonstrated that Wnt signaling, especially Wnt1 and Wnt3a, plays a pivotal role in mediating HFD-induced kidney injury." (PMID 35462998, 2022).
laryngeal squamous cell carcinoma (2 papers, 2019 to 2021). A squamous cell carcinoma that arises from the larynx. "As a classical ligand in the canonical Wnt/β-catenin signaling pathway, the role of Wnt3a in laryngeal squamous cell carcinoma (LSCC) remains unclear." (PMID 31528227, 2019).
medulloblastoma (2 papers, 2016 to 2021). A malignant, invasive embryonal neoplasm arising from the cerebellum. "Ectopic Wnt activation in primary patient-derived medulloblastoma lines proved that the activation of the Wnt/β-catenin pathway in WNT3A-conditioned medium significantly reduced the self-renewal capacity along with the Sox2 and Bmi1 expression in Group 3 and Group 4 medulloblastoma lines." (PMID 34577571, 2021).